OPTN (optineurin)
Diseases named in the same sentence as OPTN in open-access papers (continued):
Sharing a sentence is not in itself a finding about the gene and the disease.
viral infection (continued). "If this were the case it suggests that optineurin is the first TBK1 specific adaptor protein found to date and that the TBK1-optineurin complex regulates distinct aspects of the response to virus infection." (PMID 20174559, 2010). "IFNβ can induce many downstream genes; therefore, there might be a connection between viral infection and optineurin-related diseases." (PMID 37352136, 2023). "By contrast, the roles of optineurin in autophagy during viral infection are not well understood." (PMID 37352136, 2023). "This study demonstrates that IFNβ overproduction in response to viral infection is observed in ALS patient cells carrying mutations in OPTN but not in other ALS-causative genes." (PMID 37352136, 2023). "However, additional reports have highlighted OPTN’s capacity to negatively regulate the IFN response during viral infections." (PMID 38019030, 2023). "Furthermore, during viral infection, optineurin-defective cells produce an excess of IFNβ as compared with wild-type (WT) cells." (PMID 37352136, 2023). "Therefore, the relationship between optineurin and IFNβ is thought to play an important role in viral infection." (PMID 37352136, 2023). "IFNβ overproduction following viral infection was observed in several cell types, such as optineurin-deficient macrophages, microglial cells, and astrocytes and also in human ALS patient cells carrying optineurin mutations." (PMID 37352136, 2023). "Therefore, in this study, we investigated the influence of viral infection on IFNβ production in vitro and in vivo under optineurin-defective conditions." (PMID 37352136, 2023). "Optineurin is the autophagy receptor involved in aggrephagy and encoded by an ALS-linked gene, OPTN; it regulates critical processes at the crossroads of autophagy and viral infection." (PMID 31875556, 2019). "Since optineurin levels are induced following viral infection we next sought to determine whether optineurin regulates virus-triggered signalling." (PMID 20174559, 2010). "Despite the known correlation between OPTN and TBK1, we surprisingly found that viral infection in TBK1 KO cells was comparable to that in the wildtype counterparts (WT)." (PMID 38019030, 2023). "OPTN gene expression is regulated through NF-κB signalling and increases upon TLR3 activation by poly(I:C) or viral infection." (PMID 32376785, 2020). "However, further studies are needed to clarify the impact of optineurin-14.7K complex on TNFR1-induced NF-κB signaling, especially in context of viral infection." (PMID 22675546, 2012). "Therefore, the phenomenon of IFNβ overproduction in response to combined optineurin defects and viral infection is common regardless of cell type and in vitro/in vivo conditions." (PMID 37352136, 2023). "However, the role of optineurin in response to viral infection has not been fully clarified." (PMID 37352136, 2023).
Alzheimer disease (12 papers, 2014 to 2026). A progressive, neurodegenerative disease characterized by loss of function and death of nerve cells in several areas of the brain leading to loss of cognitive function such as memory and language. "However, virus-mediated overexpression of OPTN in the treatment of Alzheimer’s disease has a promising application." (PMID 35662233, 2022). "In the present study, we provided proof for the specific role of OPTN in the clearance of hyperphosphorylation Tau protein, which may provide a possible avenue in the treatment of Alzheimer’s disease." (PMID 35662233, 2022). "These bodies co-localize and display strong immunostaining for optineurin in Alzheimer’s disease." (PMID 29875767, 2018). "Optineurin is present within the inclusions in several neurodegenerative disorders, including ALS, FTD, Alzheimer’s disease, and Huntington’s disease." (PMID 29875767, 2018). "Interestingly, SOD1 showed interaction with OPTN involved in neuroinflammation, autophagy, and vesicular trafficking in ALS, FTD, Alzheimer’s disease, and Huntington’s disease." (PMID 34918006, 2022).
Paget’s disease of bone (11 papers, 2014 to 2025). "OPTN has been genetically linked to Paget's disease of bone (PDB), a chronic and disabling bone remodelling disorder often accompanied by severe orofacial deformities." (PMID 39762159, 2025). "Transcript analysis from the cerebellum and temporal cortex of AD patients highlighted that an OPTN single nucleotide polymorphism previously associated with Paget’s disease of bone was linked with increased OPTN expression." (PMID 32937909, 2020). "Genetic variants of OPTN leading to lower OPTN expression have also been identified in patients with Paget’s bone disease." (PMID 29692786, 2018). "In 2010, a GWAS into Paget's disease of the bone identified three candidate loci, one of which was mapped to OPTN on chromosome 10p13." (PMID 26044960, 2015). "Optineurin (OPTN), linked to bone disorders like Paget's disease of bone (PDB), may affect tooth root development." (PMID 39762159, 2025).
Parkinson disease (9 papers, 2015 to 2023). A progressive degenerative disorder of the central nervous system characterized by loss of dopamine producing neurons in the substantia nigra and the presence of Lewy bodies in the substantia nigra and locus coeruleus. "As optineurin acts as a receptor during mitophagy, a pathway in which its dysfunction is known to cause Parkinson’s, it is possible that hereditary or somatic mutations in genes encoding optineurin or TBK1 may lead to a Parkinsonian progression through mitophagic perturbation." (PMID 29867991, 2018). "For instance, RAB10 binds to the autophagy receptor optineurin to promote mitochondrial autophagy in Parkinson’s disease." (PMID 35030981, 2022). "One example is optineurin (OPTN) which is implicated in ALS and Parkinson’s disease." (PMID 33281563, 2020). "Moreover, parkinsonism can be involved in cases with TDP-43, ANG, OPTN, and CHMP2B mutations." (PMID 26213621, 2015). "Although the biological functions of OPTN in mitophagy have been reported to be associated with neurodegenerative diseases, including ALS, Parkinson’s disease and Huntington’s disease, the significance of OPTN in AD has not been elucidated." (PMID 34861878, 2021). "Indeed, a patient carrying the optineurin E478G mutant was clinically diagnosed with both ALS and Parkinson’s disease, with autopsy analysis showing degeneration of the substantia nigra, as well as the presence of tau-positive neurofibrillary tangles and α-synuclein-positive Lewy bodies." (PMID 29867991, 2018).
colorectal cancer (8 papers, 2018 to 2025). A primary or metastatic malignant neoplasm that affects the colon or rectum. "Additionally, OPTN plays a critical role in preventing immune evasion in colorectal cancer by maintaining interferon-gamma receptor 1 (IFNGR1) expression and supporting dendritic cell-mediated T-cell priming, thereby enhancing antitumor immune responses." (PMID 41294799, 2025). "Thus, loss of optineurin impairs the integrity of the IFNγ- and MHC-I-signaling pathways via IFNGR1 degradation, thereby driving immune evasion and intrinsic immunotherapy resistance in colorectal cancer." (PMID 34385592, 2022). "To examine the potential of WWP2 to ubiquitinate NDP52, OPTN, and SQSTM1 in cells, we cotransfected Myc-tagged WWP2 and the corresponding FLAG-tagged autophagy receptors in the HCT116 colorectal cancer cell line." (PMID 35331737, 2022).
lung carcinoma (8 papers, 2009 to 2025). "In lung cancer, where OPTN is frequently downregulated, there is a strong correlation between high OPTN levels and improved relapse-free survival." (PMID 41294799, 2025). "OPTN accelerates the autophagic activities of lung cancer and gastric cancer cells, and the suppression of OPTN expression reduces the cell division." (PMID 33600074, 2021). "To understand the molecular mechanisms involved in TNFα-induced optineurin gene expression we used human lung carcinoma cell line A549 which is responsive to TNFα." (PMID 19340308, 2009). "Indeed, overexpression of OPTN in lung cancer cell lines results in a 63% reduction in proliferation, while in vivo studies show that tumors in OPTN-HACE1-expressing cells are five times smaller than in cells lacking these proteins." (PMID 41294799, 2025). "HACE1 is also reported to ubiquitylate the autophagy receptor Optineurin (OPTN), which in turn facilitates OPTN interactions with p62/SQSTM1 to activate autophagy to inhibit growth and tumorigenicity of lung cancer cells." (PMID 30622235, 2019). "In lung cancer, HACE1 ubiquitinates OPTN and targets it for autophagic degradation." (PMID 27213432, 2016).
motor neuron disease (8 papers, 2012 to 2022). "The OPTN gene variant p.Gln314Leu has been described so far in two patients with motor neuron disease, and in 1/400 control subjects aged >56 years." (PMID 32028661, 2020). "Later on, certain mutations in OPTN were found to be associated with ALS, a fatal motor neuron disease." (PMID 29951055, 2018). "FTLD-TDP cases without motor neuron disease have been reported in association with OPTN and TBK1 (Tank-binding kinase mutations." (PMID 34093394, 2021). "Notably, none of the affected members showed any evidence of motor neuron disease or ALS at the time of writing, both clinically and on electrophysiological testing, expanding the phenotypic spectrum of OPTN mutations." (PMID 34093394, 2021).
Optic neuropathy (8 papers, 2009 to 2022). "Transgenic mice expressing the E50K mutation of OPTN, however, demonstrate an optic neuropathy that is associated with an increase in mitochondrial fission and mitophagy, along with visual impairment." (PMID 34201955, 2021). "Thus, it was designated OPTN, encoding the optineurin (for “optic neuropathy inducing”) protein." (PMID 29867991, 2018). "Mutations in its sequence have been associated with primary open-angle glaucoma (POAG), and for this reason, NRP was also named Optineurin for “optic neuropathy inducing” protein." (PMID 19609363, 2009). "We therefore cannot exclude another possibility that increasing WT OPTN expression may have a beneficial effect for glaucomatous optic neuropathy and other neurodegenerative diseases." (PMID 27654856, 2016).
Crohn disease (7 papers, 2015 to 2025). A gastrointestinal disorder characterized by chronic inflammation involving all layers of the intestinal wall, noncaseating granulomas affecting the intestinal wall and regional lymph nodes, and transmural fibrosis. "Finally, OPTN has been associated with Crohn’s disease (CD), and diminished expression of OPTN was observed in approximately 10% of CD patients." (PMID 29692786, 2018).
liposarcoma (6 papers, 2011 to 2023). A usually painless malignant tumor that arises from adipose tissue. "Mutations in several genes are causative for FALS, including fused in sarcoma/translated in liposarcoma (FUS), superoxide dismutase-1 (SOD1), TAR DNA-binding protein (TARDBP), angiogenin (ANG), vesicle-associated membrane protein B (VAPB), optineurin (OPTN), and valosin-containing protein (VCP)." (PMID 23577159, 2013). "These include the genes codingfor alsin (ALS2), vesicle associated membrane protein B (VAPB), senataxin (SETX), TAR-DNA-bindingprotein (TDP-43), fused in sarcoma or translocated in liposarcoma(FUS/TLS), and optineurin (OPTN)." (PMID 21541368, 2011).
Paget disease (6 papers, 2013 to 2021). A malignant neoplasm composed of large cells with large nuclei, prominent nucleoli, and abundant pale cytoplasm (Paget cells). "Genome-wide association studies enlarged the number of loci associated with PDB, and further fine-mapping studies, combined with functional analysis, identified OPTN and RIN3 as causal genes for Paget’s disease." (PMID 28255281, 2017).
hepatocellular carcinoma (5 papers, 2021 to 2022). A malignant tumor that arises from hepatocytes. "In addition, high expression of OPTN is associated with poor prognosis of hepatocellular carcinoma." (PMID 34616724, 2021). "Optineurin is an autophagy adaptor protein and is a marker for poor prognosis in hepatocellular carcinoma." (PMID 34885095, 2021). "Overexpression of OPTN increases mitophagy and is related to worse prognosis in hepatocellular carcinoma (HCC) patients.The expression of GAL up-regulated in neuroblastic cancers." (PMID 36419120, 2022). "Despite studies of the relation between cancer progression and autophagy adaptor proteins, there are no reports to our knowledge of a correlation between hepatocellular carcinoma (HCC) and OPTN." (PMID 33600074, 2021).
neuroblastoma (5 papers, 2019 to 2025). Neuroblastoma (NB) is the most common solid, extracranial childhood tumor. "We examined optineurin distribution in SA- and poly(I:C)-stressed WT neuroblastoma cells and found that this protein was sequestered into both types of SGs." (PMID 31875556, 2019). "Optineurin was completely deleted in the motor neuron NSC-34 cell line, while in the neuroblastoma N2A cell line, deletion efficiency was around 70%." (PMID 35743272, 2022).
proteinopathy (5 papers, 2012 to 2021). "In a recently published study, a fALS patient bearing an optineurin mutation (E478G) displayed features of several proteinopathies, including phosphorylated TDP-43, phosphorylated tau, and α-synuclein, although it was not examined whether optineurin is present in these inclusions." (PMID 29875767, 2018). "In addition to sporadic forms, several mutations in different genes, including the C9orf72 (most frequent), granulin (GRN), valosin-containing protein (VCP), TARDBP, SQSTM1 (sequestome), DCTN1 (dynactin), and OPTN (optineurin) have been reported to be associated with TDP-43 proteinopathy." (PMID 26848654, 2016). "Other two molecules OPTN and TDP43 are associated with proteinopathy, which is a characteristic of ALS." (PMID 33606761, 2021). "An increasing body of evidence indicates that TDP-43 proteinopathy underlies motor neuron degeneration caused by diverse genetic defects in various hereditary ALS, including ubiquilin 2, profilin-1, optineurin, valosin-containing protein (VCP), and C9ORF72." (PMID 23300771, 2012). "Based on these findings, and the referenced pathological findings in human cases, we suggest that α-internexin and OPTN pathology are downstream events and are not a major driver of pathology and neurodegeneration in most FUS proteinopathies." (PMID 23046583, 2012).
sarcoma (5 papers, 2011 to 2023). A usually aggressive malignant neoplasm of the soft tissue or bone. "fALS is genetically linked to at least 15 genes, including SOD1 (Cu/Zn superoxide dismutase), TARDBP (TAR DNA-binding protein), FUS (fused in sarcoma), ANG (angiogenin precursor), and OPTN (optineurin)." (PMID 34876200, 2021). "Mutations in six genes can explain about 60–70% of fALS and about 10% of sALS cases: SOD1, TARDBP, FUS (fused in sarcoma), VCP (valosin-containing protein), OPTN (optineurin), and C9orf72." (PMID 32046060, 2020).
colitis (4 papers, 2015 to 2023). Inflammation of the colon. "In agreement, loss of OPTN in mice was shown to impair cytokine production and neutrophil recruitment in a bacteria-dependent model of colitis." (PMID 29692786, 2018). "We then clarified the role of OPTN deficiency in: macrophage cytokine secretion; mouse models of bacteria-driven colitis and peritonitis; and zebrafish Salmonella infection." (PMID 26044960, 2015). "OPTN deficiency led to an accumulation of IRE1α, which enhanced colitis pathology during ER stress." (PMID 30669622, 2019). "Bacterial exposure upregulates OPTN expression, whereas OPTN deficiency results in impaired proinflammatory cytokine secretion, diminished recruitment of neutrophils into acutely inflamed tissue, an exaggerated colitis and increased susceptibility to bacterial infection." (PMID 26044960, 2015). "The function of OPTN in the regulation of intestinal homeostasis was suggested in IRE1α-driven colitis as an IRE1α-interacting protein." (PMID 30669622, 2019). "More recently, it was shown that autophagy-related genes (ATGs), such as optineurin (OPTN), transcription factor EB (TFEB) and leucine-rich repeat kinase (LRRK), are associated with increased susceptibility to colitis, suggesting that these genes are important in colonic immune homeostasis." (PMID 30669622, 2019). "This difference in response between both colitis models might suggest a specific role for OPTN in protection from bacterial infection and infection-associated IBD." (PMID 29692786, 2018). "However, contrary to the bacteria-driven colitis, OPTN knockout mice respond normally to the model of dextran sodium sulfate-induced colitis." (PMID 29692786, 2018). "The phenotype of diminished neutrophil recruitment identified in OPTN-deficient mice mirrors our published findings in CD patients, reinforcing the suggestion that reduced expression of OPTN could play an important role in the development of bacteria-driven colitis in humans." (PMID 26044960, 2015). "The genes involved in autophagy/selective autophagy, including ATG16L1, IRGM, LRRK2, ATG7, p62, optineurin (OPTN) and transcription factor EB (TFEB) in colitis and in maintaining intestinal homeostasis, are noted." (PMID 36835075, 2023).
diabetes (4 papers, 2012 to 2022). "Finally, we also used an STZ-induced diabetes rat model with intravitreal injection of lentiviral particles to validate the role of OPTN in RGCs loss and function in vivo." (PMID 35165261, 2022). "Early studies have reported the link between OPTN expression and the progression of diabetes, wherein its expression can be induced by TNF-α and interferons." (PMID 36551820, 2022). "We suggest that the succinylation of OPTN may occur in early diabetes, be involved in RGCs dysfunction, and remain stable during the course of diabetes." (PMID 35165261, 2022).
Huntington disease (4 papers, 2018 to 2023). Huntington disease (HD) is a rare neurodegenerative disorder of the central nervous system characterized by unwanted choreatic movements, behavioral and psychiatric disturbances and dementia. "Furthermore, optineurin co-localizes with htt and frequently occurs in the neuronal intracellular inclusions in Huntington’s disease and, to a lesser extent, in inclusions of the neuropil and perikaryon." (PMID 29875767, 2018).
ovarian carcinoma (4 papers, 2017 to 2025). A malignant neoplasm originating from the surface ovarian epithelium. "Consistently, immunohistochemical analysis demonstrated a marked upregulation of OPTN in primary ovarian cancer tissues." (PMID 41271632, 2025). "This study firstly demonstrates that EEF1D/PI3K/OPTN/Akt is a novel chemotherapy resistant pathway of ovarian cancer, which partially addresses the molecular mechanism of ovarian cancer chemotherapy-resistance." (PMID 35672728, 2022). "Compared with the scrambled shRNA control, OPTN KD can significantly reduce the sensitivity of human ovarian cancer cells to DDP." (PMID 35672728, 2022). "Moreover, qRT-PCR analysis indicated a significant elevation of OPTN mRNA containing the 3’UTR-LN in primary ovarian cancer samples." (PMID 41271632, 2025). "To further understand the mechanism of EEF1D affecting human ovarian cancer cell resistance, we performed OPTN knockdown of the DDP-resistant cell line SKOV3/DDP by transient lentiviral infection and found that OPTN KD reversed the effect of EEF1D." (PMID 35672728, 2022).